RNU6-992P (RNA, U6 small nuclear 992, pseudogene)
Gene: Small nuclear RNA gene on chromosome 21 (36,066,545 to 36,066,652, forward strand). Ensembl gene ENSG00000200213.
Homologues: Orthologues: chimpanzee U6 (98% identical), macaque U6 (80% identical). Paralogues in human: RNU6-797P (88% identical), RNU6-1083P (87% identical), RNU6-1091P (86% identical), RNU6-1094P (86% identical), RNU6-727P (86% identical), RNU6-11P (85% identical), RNU6-37P (85% identical), RNU6-879P (85% identical), RNU6-1209P (84% identical), RNU6-1243P (84% identical), RNU6-1309P (84% identical), RNU6-1310P (84% identical), and 1286 more.